SMIM33 (small integral membrane protein 33)
Gene: Protein-coding gene on chromosome 5 (139,471,004 to 139,473,700, forward strand). Ensembl gene ENSG00000283288.
Subcellular location: Membrane
Gene Ontology:
Cellular component: membrane
Homologues: Orthologues: chimpanzee SMIM33 (99% identical), dog SMIM33 (72% identical), rabbit SMIM33 (72% identical), pig SMIM33 (67% identical), guinea pig SMIM33 (66% identical), mouse Smim33 (60% identical).